HIF1A (hypoxia inducible factor 1 subunit alpha)
Diseases named in the same sentence as HIF1A in open-access papers (continued):
Sharing a sentence is not in itself a finding about the gene and the disease.
Peritoneal Fibrosis (continued). "Five-week intraperitoneal injection of 4.25% peritoneal dialysate remarkably increased peritoneal HIF-1α/TGF-β/p-Smad3 signaling and promoted peritoneal fibrosis and peritoneal thickening." (PMID 37251320, 2023). "Our study indicated that the HG/STAT3/HIF-1α signaling pathway might involve in all those processes and the treatment using STAT3 inhibitor could partly attenuate the progression of peritoneal fibrosis, angiogenesis and inflammation." (PMID 34193173, 2021). "LMWH was proven to mitigate pulmonary inflammation and fibrosis through the repression of HIF-1α and VEGF expression in an animal model of peritoneal fibrosis, supporting the hypothesis that LMWH offers benefits against hypoxia and inflammation." (PMID 33567713, 2021). "Among them, MMP2, BAX, ADORA3, HIF1A, PIM1, CA12, and ALOX5 exhibited higher expression in the peritoneum with encapsulating peritoneal sclerosis compared with those in the control, which might be crucial targets of baicalein against peritoneal fibrosis." (PMID 37266145, 2023).
Renal cyst (11 papers, 2011 to 2025). A fluid filled sac in the kidney. "Pseudohypoxia, characterized by the stabilization of HIF-1α under normoxic conditions, has been implicated in the pathogenesis of renal cysts." (PMID 40722668, 2025). "In ADPKD, renal cyst expansion causes localized hypoxia, resulting in stabilization of hypoxia-inducible factor-1-alpha (HIF-1α), which is degraded by the ubiquitin-proteasome system under normal O2 levels (normoxia)." (PMID 37579949, 2023). "To assess the role of HIF activation in FH-associated renal cystic disease, we determined if parallel inactivation of Hif-1α or Hif-2α would ameliorate the hyperplastic renal cystic phenotype in mice with renal tubule specific inactivation of Fh1." (PMID 22014577, 2011). "This study was motivated by histological analysis of cystic kidneys showing increased expression levels of HIF‐1α and HIF‐2α." (PMID 29263117, 2017). "For instance, activation of the Hif1α mediated hypoxic response takes place upon loss of SDH in MEFs, of FH in MEFs and renal cysts, and upon neuronal expression of the Idh1R132H mutation." (PMID 25126540, 2014). "Necdin also appears to mediate the degradation of hypoxia-inducible factor 1 alpha (HIF1α), whose overexpression is involved in renal cyst formation." (PMID 24349431, 2013). "Multiple bilateral renal cysts are characteristic of polycystic kidney disease (PKD), and its pathology has been linked to over-activation of Hypoxia-inducible factor 1-alpha (HIF-1α) in the epithelial layer and Hypoxia-inducible factor 2-alpha (HIF-2α) in the cystic wall." (PMID 28934953, 2017). "The development of renal cysts in mice deficient for the Vhl tumor suppressor gene can be repressed by genetic inactivation of the Hif dimerization partner Hif-1β (Arnt) but not Hif-1α; thus suggesting a causal role for Hif-2α in renal cyst development." (PMID 22014577, 2011). "Thus, we conclude that expression of Nrf2, and some Nrf2 target genes, are elevated in those kidney tubule cells that have lost Fh1 and line renal cysts, and that, at least in the mouse model, this occurs independently of Hif-1α and Phds and at an early stage of renal cyst formation." (PMID 22014577, 2011). "Indeed, the formation of both renal cysts and tumors was prevented upon inactivation of HIF-1α and HIF-2α in VHL-deficient mice, indicating their shared involvement during the initial stages of ccRCC development whereas only the HIF-1α isoform was evident in normal tubular cells." (PMID 36831657, 2023). "We tested renal cysts within kidney tissue obtained from the named mouse model for ICA- and HIF-1α-dependent effects on MIF as well as ABCA1 expression by immunohistochemistry." (PMID 32885302, 2020). "Additionally, a propensity for abnormal HIF-1α activation under normal oxygen tension, amplification of HIF-1α expression under low oxygen tension and the presence of renal cysts has also been demonstrated in SCD mouse models." (PMID 28934953, 2017). "Analyses of mice defective in both FH and HIF signaling reveal that inactivation of Hif-1α but not Hif-2α actually exacerbates renal cyst development." (PMID 22014577, 2011).
soft tissue sarcoma (11 papers, 2013 to 2025). A malignant neoplasm arising from muscle tissue, adipose tissue, blood vessels, fibrous tissue, or other supportive tissues excluding the bones. "Previous studies have found that the Ktrans and Kep values of patients with soft tissue sarcoma in the high HIF-1α expression group were higher than those in the low expression group, which is consistent with this study." (PMID 39723370, 2024). "There are only a few studies evaluating the relationship between HIF-1α mRNA expression and the outcome of soft tissue sarcoma patients." (PMID 30513863, 2018). "The prognostic significance of Hypoxia-inducible factor-1α (HIF-1α) in patients with bone and soft tissue sarcoma remains controversial." (PMID 27606158, 2016). "Moreover, the D* and f values of IVIM are reliable parameters for predicting the expression of HIF-1α in soft tissue sarcomas." (PMID 39906347, 2024). "High expression of the hypoxia marker CAIX in soft tissue sarcoma was found to be associated with poor survival in the Phase III adjuvant RT VorteX trial but two other hypoxia markers Hif-1a and GLUT1 were not." (PMID 37194999, 2023). "In addition, a recent meta-analysis of the prognostic significance of HIF-1α in patients with bone and soft tissue sarcoma showed that nuclear expression of HIF-1α was significantly associated with poorer disease-free and overall survival." (PMID 28558056, 2017). "Therefore, we conducted the current meta-analysis to combine published studies and to comprehensively assess the prognostic significance of HIF-1α expression in bone and soft tissue sarcoma." (PMID 27606158, 2016). "In conclusion, HIF-1α expression might be an effective predicative factor of poor prognosis for bone and soft tissue sarcoma." (PMID 27606158, 2016). "In conclusion, this meta-analysis demonstrates that HIF-1α expression may be an effective predicative factor of poor prognosis for bone and soft tissue sarcoma." (PMID 27606158, 2016). "Therefore, HIF-1α may be an effective prognostic factor of poor prognosis for bone and soft tissue sarcoma." (PMID 27606158, 2016). "The clinical relevance of these findings is underscored by prior studies linking high expression of HIF-1α and CA9 to increased metastatic potential and poorer prognosis in soft tissue sarcomas." (PMID 41174561, 2025). "Previous studies have shown that HIF-1α expression in soft tissue sarcomas are regulated in a non-oxygen-dependent pattern." (PMID 40809031, 2025).
thrombosis (11 papers, 2018 to 2025). "Related studies have also confirmed that HIF-1α can regulate the expression of NLRP3 in a venous thrombosis model." (PMID 35449811, 2022). "We also previously showed that pulmonary thrombosis increases the levels of HIF1α and HIF2α in murine lungs, enhances the levels of tumorigenic factors in the circulation, and promotes pulmonary tumorigenesis." (PMID 36291563, 2022). "Our study showed a direct association between nucleotide-binding domain, leucine-rich-containing family, pyrin domain containing 3 (NLRP3) inflammasome complex and hypoxia-inducible factor 1-alpha (HIF-1α) in hypoxia-induced thrombosis." (PMID 31653092, 2019). "In addition, the genetic blockade of HIF-1α expression or IL-1β production decreased thrombus formation in a flow restriction-induced thrombosis model in rats." (PMID 31552036, 2019). "Hypoxia-inducible factor 1-alpha (HIF-1α) is an important regulatory protein in the hypoxic environment that mediates Nod-like receptor protein-3 (NLRP3) expression and increased IL-1β secretion and plays a vital role in the process of venous thrombosis." (PMID 37680629, 2023).
tongue squamous cell carcinoma (11 papers, 2012 to 2026). A squamous cell carcinoma that arises from the tongue. "The same expression pattern of HIF-1α and Twist2 is also observed in tongue squamous cell carcinoma where it is associated with a shorter disease-free survival." (PMID 23946798, 2013). "This study was carried out to analyze the effect of HIF-1α on the biological activation of human tongue squamous cell carcinoma (TSCC) SCC-15 cells." (PMID 25816356, 2015). "The aim of the present study was to investigate the expression of hypoxia-inducible factor-1α (HIF-1α) in tongue squamous cell carcinoma (TSCC) and to assess its possible impact on prognosis." (PMID 23251251, 2013). "In tongue SCC tissues, hypoxia inducible factor (HIF)-1α, HIF-2α, and Twist-2 were overexpressed and the overexpression of these molecules, except HIF-2α, was associated with a shorter disease-free survival." (PMID 22548191, 2012). "It was suggested that coexpression of more than two markers from HIF-1α and Twist2 be a significant prognostic predictor in patients with tongue SCC." (PMID 22548191, 2012). "However, whether Rha can lessen Cis resistance in tongue squamous cell carcinoma (TSCC) by mediating HIF‐1α activity is unclear." (PMID 40608530, 2025). "To analyze whether the role of autophagy affecting the glycosylation in tongue squamous cell carcinoma is dependent on the variation of the hypoxia, we designed the OGT protein detected based on the autophagy knockdown while HIF-1α was inhibited." (PMID 26640316, 2015).
acute lung injury (10 papers, 2013 to 2026). A condition of lung damage that is characterized by bilateral pulmonary infiltrates (pulmonary edema) rich in neutrophils, and in the absence of clinical heart failure. "In support of this regulatory function of HIF-1α, pharmacological in vivo studies in acute lung injury (ALI) have shown that HIF-1α stabilization attenuates pulmonary oedema and lung inflammation." (PMID 33031374, 2020). "Moreover, HIF-1α was found to be activated in alveolar type 2 cells (target for SARS-CoV-2), during acute lung injuries while Ang II-induced renal injury requires activation of HIF-1α." (PMID 36091390, 2022). "Recent single-cell transcriptomic analyses in murine acute lung injury (ALI) models have revealed that dysfunction of SDHA leads to intracellular succinate accumulation and Hypoxia-Inducible Factor 1 Alpha Subunit (HIF-1α) stabilization, driving a metabolic switch of AT2 cells toward glycolysis." (PMID 41007859, 2025).
acute lymphoblastic leukemia (10 papers, 2015 to 2025). Leukemia with an acute onset, characterized by the presence of lymphoblasts in the bone marrow and the peripheral blood. "Leukemic cells from bone marrow of childhood acute lymphoblastic leukemia (ALL) have shown an overexpression of a key marker of hypoxia called hypoxia inducible factor (HIF-1α)." (PMID 27658583, 2016). "In acute lymphoblastic leukemia (ALL), HIF1α expression has been measured via immunostaining of BM biopsies, which revealed that HIF1α is overexpressed in BM of childhood ALL and correlates with worse overall survival." (PMID 36059690, 2022). "In acute lymphoblastic leukemia (ALL), levels of HIF-1α, GLUT1, GLUT3, CA4, and glyceraldehyde-3-phosphate dehydrogenase (GAPDH) were significantly greater in leukemic cells compared to healthy blood cells." (PMID 26437434, 2015). "In acute lymphoblastic leukemia (ALL), HIF-1α functions as an oncogenic driver." (PMID 40791591, 2025). "For instance, HIF-1α is overexpressed in clusters of bone marrow (BM)-resident leukemic cells in pediatric acute lymphoblastic leukemia (ALL) cases but was found to be absent in normal BM." (PMID 36231060, 2022). "The clinical implications of HIF-1α in the regulation of YY1 were investigated by evaluation of expression of HIF-1α and YY1 in 108 peripheral blood samples and by RT-PCR in 46 bone marrow samples of patients with pediatric acute lymphoblastic leukemia (ALL)." (PMID 35163649, 2022).
aneurysm (10 papers, 2016 to 2023). Bulging or ballooning in an area of an artery secondary to arterial wall weakening. "Previous studies have demonstrated that HIF-1α expression is negatively associated with aneurysm formation, while others demonstrate a positive association." (PMID 31546645, 2019). "Increased expression of HIF-1α has been found in human and experimental aneurysms, along with histological evidence of mural leukocyte infiltration and reduced angiogenesis." (PMID 37283588, 2023). "Variations in CA IX amount are consistent with results of the Wang group who reported large differences in HIF-1α mRNA expression detected within a human aneurysm cohort." (PMID 35055064, 2022). "Lately, we were able to demonstrate a positive effect on halting AAA growth by RNA interference targeting the long noncoding RNA H19, which represses HIF1α signaling and its apoptotic effect on vascular smooth muscle cells (VSMCs) during aneurysm progression." (PMID 34185710, 2021). "The secondary increase of TGF-β and NOX4-induced dysregulation of hypoxia-inducible factor-1 (HIF-1α)/vascular endothelial factor (VEGF) signaling further contributes to aneurysm progression." (PMID 33807627, 2021). "Interference with the HIF1α/VEGF/VEGFR axis has been shown multiple times to hinder aneurysm growth in mouse models." (PMID 34185710, 2021). "Our study confirmed the critical role of HIF-1 signaling in aneurysm and atherosclerosis, HIF-1α signaling pathway was involved in the formation and rupture of AS plaques." (PMID 35069552, 2021). "In future experiments, we hope to elucidate the role of HIF-1α as it relates to aneurysm induction and progression, particularly concerning the activation and effector function of OLCs." (PMID 31546645, 2019). "Certainly, to clarify the exact role of HIF1a in PI3K/AKT pathway during aneurysm progression, further research is anticipated." (PMID 29123158, 2017). "We found that these aneurysm prone factors significantly and concurrently induced HIF-1α, MMP-2 and MMP-9 expression (n = 4–5)." (PMID 27363580, 2016). "In addition, quercetin-induced aneurysm inhibition is accompanied by the reduced HIF-1α/VEGF signaling pathway." (PMID 32908926, 2020). "The function of HIF-1α in aneurysms remains unclear, as multiple studies have demonstrated seemingly contradictory results." (PMID 31546645, 2019). "Additionally, more OLCs from aneurysms express HIF-1α, and produce more MMP-9 and cathepsin K, than myeloid cells from the same tissue." (PMID 31546645, 2019). "We observed increased HIF-1α expression in TPMs from mouse CaPO4-induced aneurysms (21.73% ± 6.202% vs. 67.7% ± 2.195%, p < 0.001), AngII-induced aneurysms (5.572% ± 1.356% vs. 56.22% ± 5.458%, p < 0.001), and human AAAs (20% ± 4.952% vs. 82.8% ± 11.58%, p < 0.01) (respectively)." (PMID 31546645, 2019). "Previous experiments demonstrate the ability of the HIF1a inhibitor to both suppress experimental AAA initiation and stabilize existing aneurysms, through mechanisms likely related to impair mural macrophage infiltration and angiogenesis." (PMID 29123158, 2017). "Moreover, aneurysm samples showed upregulation of genes involved in mitochondrial uncoupling and glycolytic rewiring (UCP2, HIF1A, and MYC)." (PMID 33709773, 2021). "Previously, HIF-1α has been described as a potentially important pathway in the development of aneurysms in the mouse AngII model and in human tissue, but it has not been described in the mouse CaPO4 model." (PMID 31546645, 2019). "Additionally, we compared HIF-1α expression between myeloid and TPM cell populations from mouse and human aneurysms." (PMID 31546645, 2019). "We evaluated the percentage of live cells positive for HIF-1α via flow cytometry, and compared to controls, we observed increased HIF-1α expression in CaPO4 (0.1294% ± 0.01719% vs. 1.774% ± 0.2277%, p < 0.01) and AngII (0.7133% ± 0.08819% vs. 3.703% ± 0.5235%, p < 0.01) mouse models of aneurysm." (PMID 31546645, 2019).
B-cell lymphoma (10 papers, 2012 to 2024). "Our current data are the first to identify a new function for LMP2A as a positive regulator of HIF-1α and ATP production in B cell lymphomas through a post-transcriptional mechanism that is dependent on p70S6K and 4E-BP1." (PMID 38612754, 2024). "Suberoylanilide hydroxamic acid (SAHA, vorinostat), a second-generation HDACi, can inhibit cell proliferation and induce apoptosis by inhibiting the expression of HIF-1α in B-cell lymphoma in vitro and in vivo." (PMID 36982568, 2023). "Ectopic expression of a stable form of HIF1 increases MYC-mediated tumorigenesis, while knockdown of HIF1α in B-cell lymphoma P493 cells suppresses its tumorigenesis." (PMID 33251216, 2020). "Moreover, HIF-1α plays a crucial role in the pathogenesis of PEL, an aggressive B-cell lymphoma with a poor prognosis caused by KSHV, which promotes the activity of HIF-1α and, in turn, activates the KSHV gene." (PMID 36982568, 2023). "Furthermore, inhibitors of mTOR were less successful in clinical studies in the treatment of B cell lymphomas than expected based on pre-clinical experiments, suggesting the need for multi-target approaches that include inhibitors of mTOR in conjunction with HIF-1α." (PMID 38612754, 2024). "For instance, the EBV oncoprotein LMP1 can bind to PARP1 and co-activate HIF-1α by the addition of the activating H3K27ac mark to the promoters of HIF-1α target genes, ultimately leading to a glycolytic switch in B cell lymphoma cell-line models." (PMID 37298494, 2023). "Notably in our study, FIH status did not affect Il10 mRNA expression and the observed tumor suppressive function of FIH is more HIF2α-dependent than HIF1α, suggesting that FIH might suppress B-cell lymphoma via an Il10-independent pathway." (PMID 38422022, 2024).